UBE2CP3 (ubiquitin conjugating enzyme E2 C pseudogene 3)
Gene: Processed pseudogene on chromosome 4 (57,072,683 to 57,073,132, forward strand). Ensembl gene ENSG00000250384.
Diseases named in the same sentence as UBE2CP3 in open-access papers:
UBE2CP3 is named in the same sentence as 15 diseases in open-access papers, as found by Europe PMC text mining. Sharing a sentence is not in itself a finding about the gene and the disease. The quoted sentences say what the papers report.
gastric cancer (7 papers, 2021 to 2023). A primary or metastatic malignant neoplasm involving the stomach. "In this study, we revealed that lncRNA UBE2CP3 was aberrantly upregulated in multiple independent gastric cancer cohorts, and its overexpression was clinically associated with poor prognosis in GC." (PMID 34274947, 2021). "The UBE2CP3 pseudogene drives gastric cancer metastasis by sponging miR-138-5p and mediating ITGA2 expression." (PMID 36348434, 2022). "To date, our work present here represents the first data on the precise function of lncRNA UBE2CP3 in gastric cancer." (PMID 34274947, 2021). "To further verify the upregulation of UBE2CP3 in GC, we also examined the UBE2CP3 expression profile in human gastric cancer tissues and normal stomach tissues by analysis of the available expression data in GEO dataset." (PMID 34274947, 2021). "Similarly, the UBE2CP3 expression in poorly differentiated gastric cancer tissues was higher than that in moderately or highly differentiated gastric cancer tissues (p < 0.0001)." (PMID 34274947, 2021). "In addition, the expression of UBE2CP3 was positively correlated with lymph node metastasis of gastric cancer." (PMID 34274947, 2021). "We previously reported that IGFBP7 plays a role in maintaining mRNA stability of oncogenic lncRNA UBE2CP3 by RNA-RNA interaction in gastric cancer (GC)." (PMID 36681667, 2023). "The results revealed that knockdown of UBE2CP3 significantly inhibited the gastric cancer cells migration and invasion, while overexpression of UBE2CP3 in turn remarkably promotes GC cell migration and invasion." (PMID 34274947, 2021). "In other words, it’s the dysregulation of the ceRNA network “UBE2CP3/miR-138/ITGA2” that drives the malignant progression and metastasis of gastric carcinoma." (PMID 34274947, 2021). "However, the biological function of UBE2CP3 in gastric cancer (GC) remains unknown." (PMID 34274947, 2021).
hepatocellular carcinoma (7 papers, 2017 to 2024). A malignant tumor that arises from hepatocytes. "The lncRNA ubiquitin conjugating enzyme E2C pseudogene 3 (UBE2CP3) was found to promote the secretion of vascular endothelial growth factor (VEGF) in hepatocellular carcinoma, as demonstrated in a co-culture system." (PMID 32640630, 2020). "Subsequent knockdown experiments revealed that this VEGF secretion is regulated through the activation of the ERK1/2/HIF-1α/VEGF pathway following frequent upregulation of UBE2CP3 in hepatocellular carcinoma cell." (PMID 32640630, 2020). "In addition, in hepatocellular carcinoma, lnc RNA ubiquitin conjugated enzyme E2C pseudogene 3 (UBE2CP3) has been reported as an oncogene that promotes tumor metastasis." (PMID 33109235, 2020). "lncRNA (UBE2CP3) enhances VEGFAsecretion and promotes angiogenesis in HCC cells by activating ERK1/2/HIF-1α/VEGFAsignaling in hepatocellular carcinoma." (PMID 39682093, 2024). "We aimed to elucidate the diagnostic efficacy of eight serum lncRNAs HULC, MALAT1, Linc00152, PTENP1, PTTG3P, SPRY4-IT1, UBE2CP3, and UCA1 and their combinations for the diagnosis of hepatocellular carcinoma (HCC)." (PMID 32733618, 2020).
liver cancer (2 papers, 2021 to 2023). An epithelial or non-epithelial malignant neoplasm that arises from the liver. "In the previous studies, the actions of numerous lncRNAs, such as ubiquitin-conjugating enzyme E2C pseudogene 3 (UBE2CP3) 17, lnc-DILC (lncRNA downregulated in liver cancer stem cells) 18, and cancer susceptibility candidate 2 (CASC2) 19, have been confirmed in hepatocarcinogenesis." (PMID 36619232, 2023).
liver diseases (1 paper, 2020). "The levels of serum HULC, MALAT1, Linc00152, PTTG3P, SPRY4-IT1, UBE2CP3, and UCA1 were significantly higher in HCC patients than in patients with benign liver diseases and healthy controls, whereas serum PTENP1 was significantly decreased in HCC patients compared with healthy participants." (PMID 32733618, 2020).
stomach cancer (1 paper, 2021). "It’s found that the overexpression of UBE2CP3 was positively correlated with the degree of malignancy of gastric tumors." (PMID 34274947, 2021).
tumor (7 papers, 2017 to 2025). "In breast cancer, UBE2CP3 is highly expressed, promotes tumour angiogenesis, and is also associated with poor prognosis." (PMID 35052495, 2022). "Taken together, overexpression of UBE2CP3 promotes tumor progression via cascade amplification of ITGA2 upregulation in GC." (PMID 34274947, 2021). "The results also showed that lncRNA UBE2CP3 transcripts were expressed at higher levels in GC tissue than non-tumor tissue from the same donor (P < 0.001)." (PMID 34274947, 2021). "In the tumor cells, the dysregulation of UBE2CP3 will lead to the amplified dysregulation of miR-138-5p and ITGA2." (PMID 34274947, 2021). "Mice injected with cells knocking down UBE2CP3 had a lower EV density in the tumor tissue than the mice injected with sh-control cells." (PMID 29866133, 2018). "UBE2CP3 expression was higher in HCC tissues than in para-tumor tissues and was up-regulated in high EV density tissues compared with its level in low EV density tissues." (PMID 29866133, 2018). "In this study, we found that UBE2CP3 expression was higher in HCC tissues than in para-tumor tissues and was up-regulated in tissues with high EV density." (PMID 29866133, 2018). "Our study suggests that UBE2CP3 can enhance the interaction between HCC tumor cells and HUVECs and promote HCC tumorigenicity by facilitating angiogenesis." (PMID 29866133, 2018). "The long non-coding RNA (lncRNA) ubiquitin conjugating enzyme E2C pseudogene 3 (UBE2CP3) has been reported as an oncogene that promotes tumor metastasis in HCC." (PMID 29866133, 2018). "The clinical results showed that UBE2CP3 expression and EV density are both significantly correlated with metastasis (i.e., positively correlated with tumor number) and poor prognosis in HCC patients." (PMID 29866133, 2018). "Expression of ubiquitin-conjugating enzyme E2C pseudogene 3 (UBE2CP3) is higher in HCC than adjacent non-tumor tissues and in tissues with high endothelial vessel density." (PMID 30477236, 2018). "Specifically, UBE2CP3 promotes HCC cell secretion of VEGFA into the tumor microenvironment by activating the ERK/p70S6K/HIF-1α pathway; this VEGFA alters EC proliferation, migration and tube formation capacities." (PMID 29866133, 2018). "The lncRNA ubiquitin conjugating enzyme E2C pseudogene 3 (UBE2CP3) is recognized as an oncogene and has been reported to promote tumor metastasis by inducing epithelial–mesenchymal transition (EMT) in HCC." (PMID 29866133, 2018). "The lncRNA UBE2CP3 transcripts were expressed at higher levels in HCC tissue than non-tumor tissue from the same donor, after normalizing to U6 expression (P < 0.001)." (PMID 29029437, 2017). "Similarly, subcutaneously implanted tumor model in nude mice showed that UBE2CP3 depletion significantly represses GC tumor growth in vivo." (PMID 34274947, 2021). "Modulating tumor angiogenesis by inhibiting UBE2CP3 expression may be a potential strategy for HCC prevention and treatment." (PMID 29866133, 2018). "Our results suggest that in HCC, UBE2CP3 indirectly enhances tumor cell-induced angiogenesis." (PMID 29866133, 2018). "Since the EMT process has been suggested to be closely related to the tumor extracellular microenvironment, we hypothesized that UBE2CP3 may play an important role in the tumor extracellular microenvironment." (PMID 29866133, 2018). "In this study, we found that the expression of UBE2CP3 was up-regulated in HCC tissues compared to the levels in para-tumor tissues, and compared to its expression in tissues with low EV density, UBE2CP3 expression was up-regulated in tissues with high EV density." (PMID 29866133, 2018). "In addition, univariate analysis of prognostic variables revealed that lncRNA UBE2CP3 expression (P = 0.001), Edmondson grade (P = 0.015), and tumor size (P = 0.012) were significantly related to overall survival in patients with HCC." (PMID 29029437, 2017).
tumor (continued). "Our results demonstrated that the ERK/p70S6K/HIF-1α signalling pathway may be partially responsible for the UBE2CP3-induced accumulation of VEGFA and leads to tumor cell-mediated angiogenesis." (PMID 29866133, 2018). "Xenograft models in nude mice with cells over-expressing and silencing lncRNA UBE2CP3 demonstrated that lncRNA UBE2CP3 was not involved in HCC tumor growth." (PMID 29029437, 2017). "UBE2CP3 has been shown to promote hepatocyte VEGFA secretion into the tumor microenvironment and enhance tumor cell-induced angiogenesis through activation of the ERK/p70S6K/HIF-1α pathway, while ERK signaling has previously been noted to play a role in the regulation of tumor EMT." (PMID 40028033, 2025). "Furthermore, patients overexpressing UBE2CP3 had a median overall survival (OS) that was lower than that of HCC patients with tumours that did not express UBE2CP3." (PMID 35052495, 2022). "Interestingly, the expression of UBE2CP3 is restricted to the tumour and has not been detected in the para-tumour tissue." (PMID 35052495, 2022).
cancer (2 papers, 2017 to 2021). A tumor composed of atypical neoplastic, often pleomorphic cells that invade other tissues. "To explore the biological function of UBE2CP3 in cancer, we first conducted the pan-cancer analysis of UBE2CP3 expression in the different types of TCGA cancer cohorts containing the corresponding normal tissues." (PMID 34274947, 2021). "Taken together, we mapped the working model of UBE2CP3’s cancer-promoting mechanism." (PMID 34274947, 2021).
UBE2CP3 also shares sentences with these, for which no sentence is quoted: breast carcinoma (1 paper); colon cancer (1); esophageal cancer (1); head and neck squamous cell carcinoma (1); infection (1); liver cirrhosis (1); lymph node metastasis (1); rectum adenocarcinoma (1).